C10orf88 (chromosome 10 open reading frame 88)
Description:
ATPase that regulates mitochondrial ABC transporters ABCB7, ABCB8/MITOSUR and ABCB10. Regulates mitochondrial ferric concentration and heme biosynthesis and plays a role in the maintenance of mitochondrial homeostasis and cell survival.
Synonyms: PAAT; FLJ13490; Em:AC073585.5
Tractability: PROTAC: ubiquitination databases record sites on it.
Gene: Protein-coding gene on chromosome 10 (122,930,901 to 122,954,311, reverse strand). Ensembl gene ENSG00000119965.
Subcellular location: Cytoplasm; Mitochondrion
Gene Ontology:
Molecular function: ATP hydrolysis activity; protein binding; identical protein binding
Cellular component: cytoplasm; mitochondrion
Genetic constraint (gnomAD): Loss-of-function variants: 23 observed, 31.52 expected, observed/expected ratio (o/e) 0.73, 90% interval 0.52 to 1.03. The upper end of that interval is the gene's LOEUF score, 1.03, which puts it in group 4 of 6, group 1 being the genes least tolerant of losing a copy. Missense variants: 465 observed, 488.81 expected, observed/expected ratio (o/e) 0.95, 90% interval 0.88 to 1.03. Synonymous variants: 179 observed, 184.21 expected, observed/expected ratio (o/e) 0.97, 90% interval 0.86 to 1.1.
Homologues: Orthologues: chimpanzee C10H10orf88 (98% identical), macaque C9H10orf88 (94% identical), guinea pig C10orf88 (75% identical), rat C1h10orf88 (72% identical), dog C28H10orf88 (72% identical), mouse 2310057M21Rik (71% identical), tropical clawed frog c7h10orf88 (30% identical), zebrafish si:rp71-19m20.1 (22% identical).
Diseases named in the same sentence as C10orf88 in open-access papers:
C10orf88 is named in the same sentence as 1 disease in open-access papers, as found by Europe PMC text mining. Sharing a sentence is not in itself a finding about the gene and the disease.
C10orf88 shares sentences with these, for which no sentence is quoted: copy number variation (1 paper).